CD74 (CD74 molecule)
Diseases named in the same sentence as CD74 in open-access papers (continued):
Sharing a sentence is not in itself a finding about the gene and the disease.
chronic lymphocytic leukemia (13 papers, 2013 to 2026). "Specifically, activation of CD74 in B cell chronic lymphocytic leukemia cells triggered a malignant cell survival cascade via NF-κB activation, suggesting that CD74 acts as a survival receptor enabling persistence of mature B cells after differentiation." (PMID 41597203, 2026). "Many studies have demonstrated that CD74 expression is regulated in various cancers, including chronic lymphocytic leukemia (CLL), and correlates with poor prognosis." (PMID 39576827, 2024). "The most well-characterized CD74 inhibitor is Milatuzumab, a monoclonal antibody approved for the treatment of chronic lymphocytic leukemia with acceptable side effects in humans including leukopenia, rash, nausea, and vomiting at low grade." (PMID 29875777, 2018). "The aim of the study was to evaluate the expression of CD74 in chronic lymphocytic leukemia patients with combination with other known prognostic factors." (PMID 23572149, 2013). "The aim of this study was to assess the expression of CD74 in chronic lymphocytic leukemia cells in relation to known prognostic factors." (PMID 23572149, 2013). "The CD74 sequence was determined from a gene expressed in chronic lymphocytic leukemia." (PMID 41439980, 2025). "Moreover, MIF/CD74 signaling also activates the NF-κB signaling pathway in chronic lymphocytic leukemia." (PMID 36496973, 2022). "We showed higher expression of CD74 in CLL and its correlation with known prognostic factor ZAP70 and stage of the disease in chronic lymphocytic leukemia." (PMID 23572149, 2013). "It has been reported that activation of Cd74 by MIF can result in upregulation of TAp63, which further leads to increased expression of integrin VLA-4, resulting in enhanced migration and survival of chronic lymphocytic leukemia cells." (PMID 34836197, 2021). "The anti-CD74 mAb milatuzumab has already been tested in Phase II studies (NCT00868478 and NCT00989586) for the treatment of chronic lymphocytic leukemia and in combination with the anti-CD20 mAb veltuzumab in relapsed and refractory B-cell non-Hodgkin’s lymphoma." (PMID 31635049, 2019). "In B-cell chronic lymphocytic leukemia (B-CLL), secreted MIF enhances tumor cell survival via activation of the CD74/CD44–IL8 axis and the ERK pathway." (PMID 40835826, 2025). "MIF binding to CD74 induces a signaling cascade resulting in the release of its cytosolic intracellular domain (CD74-ICD), which regulates transcription in naïve B and chronic lymphocytic leukemia (CLL) cells." (PMID 39576827, 2024).
metastatic melanoma (13 papers, 2018 to 2025). A melanoma that has spread from its primary site to another anatomic site. "MIF/CD74 activity promotes immunosuppressive signaling in macrophages and dendritic cells and inhibition of this signaling re-establishes the antitumor immune response in metastatic melanoma." (PMID 36496973, 2022). "Indeed, a new 2018 study used the Id-CDR-based peptide, C36L1, which binds to the MIF receptor, CD74, to reactivate macrophages and dendritic cells in both in vitro and in vivo metastatic melanoma models." (PMID 31013837, 2019). "Blockade of CD74 related immunosuppressive signaling may restore anti-tumor immune response in metastatic melanoma, suggesting the crucial role of CD74 in immunotherapy." (PMID 31212865, 2019). "While CD74 typically acts as a chaperone for MHC molecules under normal conditions, it gets targeted by MIF in metastatic melanoma, altering its immunogenic role and reducing the DCs’ ability to expand antitumor CD8 + T cells." (PMID 38777826, 2024). "Moreover, a study illustrated that blockading CD74-MIF on macrophages and DCs can recover antitumor activity of immune system in metastatic melanoma." (PMID 35769782, 2022). "Blocking MIF signaling through CD74 on MOs and DCs, using the C36L1 Ig-CDR-based peptide, restores the pro-inflammatory functions of MOs and DCs thereby harnessing the immune response against metastatic melanoma." (PMID 29875777, 2018). "Although this study was originally grounded on the rationale that MIF/CD74 axis drives poor immunogenicity in metastatic melanoma, a significant limitation of this study is the lack of functional validation for the hypoxia-related results in MIF/CD74 dependent signalling." (PMID 37454231, 2023). "Blocking specific mechanisms of immunogenicity suppression, such as MIF/CD74 in metastatic melanoma, as opposed to a ‘shotgun’ approach of promoting more GM-CSF expression to increase overall immune activity, could offer a more precise, efficient, and potentially less toxic therapeutic route." (PMID 37454231, 2023).
colorectal cancer (12 papers, 2021 to 2025). A primary or metastatic malignant neoplasm that affects the colon or rectum. "Previous studies have reported the interaction of fibroblasts and myeloid cells in colorectal cancer activated protumorigenic signaling pathways such as MIF/CD74 and promoted the aggressive phenotypes." (PMID 38880903, 2024). "In fact, research has shown that MSI-H colorectal cancer patients with a high abundance of CD68+CD74+ macrophages can benefit significantly from the treatment of nivolumab and pembrolizumab." (PMID 36238279, 2022). "Interestingly, similar findings have been reported in colorectal cancer (CRC), where the MIF/CD74 pathway has been implicated in regulating disease progression." (PMID 41562071, 2025). "We meticulously analyzed the intricate regulatory network inside the TME of colorectal cancer, namely the immune signaling interactions between tumor cells and macrophages via the MIF-(CD74+CD44) signaling pathway." (PMID 40842994, 2025). "During the process of liver metastasis in colorectal cancer, the interaction between MIF and its receptors, CD74 and CXCR4, is markedly intensified, promoting tumor cell invasion and migration." (PMID 41127012, 2025). "Interestingly, a recent study found that in an IFN‐high immunophenotype of colorectal cancer that is sensitive to PD1 immunotherapy, CTLs can induce the upregulation of genes related to antigen processing and presentation, such as CD74, in adjacent tumour cells." (PMID 40356247, 2025). "Using public scRNA-seq data of patients with colorectal cancer, we observed a significant negative correlation between the proportions of SPP1+ TAMs and CD74+ TAMs, further supporting the distinct evolutionary paths of inflammatory (i.e., SPP1+) and antigen-presenting (i.e., CD74+) TAMs." (PMID 40312419, 2025).
pneumonitis (12 papers, 2020 to 2025). An inflammatory process affecting the lung parenchyma. "The level of anti-BP-180 IgG is suspected to be associated with skin irAEs, and anti-CD74 antibodies are expected to be associated with pneumonitis." (PMID 34867321, 2021). "Using ELISA, baseline anti-GNAL and elevation of both anti-GNAL and anti-ITM2B antibodies during treatment were shown to be associated with hypophysitis in 20 patients and anti-CD74 antibodies with pneumonitis occurrence in 32 patients with solid tumors." (PMID 33643899, 2020). "CD74 has been investigated as a biomarker of pneumonitis in renal cell carcinoma, but future work is needed to examine its potential as a biomarker of other irAEs and in other cancers." (PMID 38730725, 2024). "The authors found increased levels of anti-CD74 autoantibodies in two patients with ICI-pneumonitis from a discovery cohort." (PMID 34680601, 2021). "These facts indicate the pathogenic role of CD74 and its autoantibodies in the development of ICI-pneumonitis." (PMID 34680601, 2021). "In a study of patients with various solid tumors (including renal cell carcinoma) who received combination anti-CTLA-4 and anti-PD-1 ICB treatment, a higher expression of CD74 autoantibodies measured in the serum before ICB therapy was correlated with the development of irAE pneumonitis." (PMID 38730725, 2024). "For example, anti-CD74 antibodies were associated with pneumonitis in our previous study, but this was not present in our panel." (PMID 38152395, 2023). "The authors identified increased pre-treatment anti-guanine nucleotide-binding protein G subunit alpha (anti-GNAL) which was associated with hypophysitis (OR = 2.66; 95% CI 1,14-7.29 p = 0.02, AUC = 0.79), and anti-CD74 levels with pneumonitis (OR = 1.25; 95% CI 1.03-1.52 p = 0.03, AUC = 0.76)." (PMID 36713389, 2022). "In normal human lung tissue, CD74 is expressed at modest levels; however, its expression is dramatically increased in lung tissues affected by ICI-induced pneumonitis." (PMID 40963607, 2025). "Modest levels of CD74 were expressed in normal human lung tissue, while dramatically increased levels of CD74 were found in lung tissues from ICI-pneumonitis." (PMID 34680601, 2021). "Further, levels of anti-CD74 autoantibodies, pre- and post-treatment, were significantly increased in patients with pneumonitis compared with those without pneumonitis." (PMID 34680601, 2021). "A follow-up study investigated CD74 autoantibody levels in the plasma of Japanese patients with renal cell carcinoma receiving ICB combination or monotherapy; in this work, CD74 autoantibody levels did not represent a predictive biomarker of pneumonitis irAE or higher-grade irAEs." (PMID 38730725, 2024). "Furthermore, CD74 protein was expressed at much higher levels in the lungs of patients with ICB-induced pneumonitis compared to normal lung tissue, suggesting that the high expression of CD74 autoantibodies may have relevance in the mechanism of ICB-induced pneumonitis." (PMID 38730725, 2024).
cervical cancer (11 papers, 2017 to 2026). A primary or metastatic malignant neoplasm involving the cervix. "Most recently, targeting TAM-derived CD74 in cervical cancer models was shown to potentiate immunotherapeutic responses." (PMID 41597203, 2026). "Further analysis of a larger cohort is necessary to gain an insight into the possible predictive role of CD74 in cervical cancer in different patient age groups and cancer stages." (PMID 35208514, 2022). "In cervical cancer, CD74 expression in tumor-associated macrophages (TAM) was shown to modulate response to therapy; CD74 blockade augmented the efficacy of neoadjuvant chemotherapy when combined with PD-1 checkpoint inhibition, implicating CD74 as a therapeutic co-target." (PMID 41597203, 2026). "Likewise, CD74 is reported that it may play an important role in the pathogenesis and angiogenesis of cervical cancer as well as the influence of the HPV." (PMID 31881980, 2019). "The research on the correlation between CD74 protein expression and clinical outcomes in specific cancer types (e.g., NSCLC, cervical cancer) is ongoing." (PMID 38280003, 2024). "The cell surface expression of CD74 and CD44 was appraised in CAMA-1, MDA-MB-231, MDA-MB-435, Raji and cervical cancer HeLa cells." (PMID 29190904, 2017). "In cervical cancer, CAFs and B cells communicate through MIF-(CD74+CXCR4) and MIF-(CD74+CD44)." (PMID 38157264, 2023). "Background and Objectives: Abnormal expressions of CD74 and human leukocyte antigen-DR alpha (HLA-DRA) have been reported in various cancers, though their roles in cervical cancer remain unclear." (PMID 35208514, 2022). "The roles of CD74 and HLA-DRA in cervical cancer development are relatively unknown." (PMID 35208514, 2022).
Obesity (11 papers, 2016 to 2026). Accumulation of substantial excess body fat. "Furthermore, CD74 inhibition has been shown to reduce inflammation in adipose tissue and mitigate insulin resistance associated with high-fat-diet-induced obesity." (PMID 39936965, 2025). "CD74 is a type II transmembrane protein, and MIF/CD74 signaling affects M1 macrophage polarization in obesity-related adipose tissue inflammatory disease." (PMID 37431183, 2023). "Differences in the exposed loop regions of helminth MIF may differentially affect its interactions with CD74 or other receptors, thereby conferring anti-inflammatory and anti-obesity properties." (PMID 41596532, 2026). "As with neutralizing MIF, CD74 knockout also significantly reduced adipocyte hypertrophy and body weight gain following HFD feeding, suggesting that CD74 may be a key regulator of the MIF/AMPK/JNK/HSL pathway during obesity." (PMID 37935315, 2024). "The immune-related and cell signaling function of Cd74 and EiF3jl may be representative of residual obesity-related gene expression changes." (PMID 39273278, 2024). "Additionally, CD74 expression has been shown to correlate with obesity-induced increases in body weight and metabolic changes in adipose tissue, and is increased in hippocampus of HFD-fed mice." (PMID 30396359, 2018). "Adipocytes from humans with obesity had increased expression of multiple MHCII-related genes (CIITA, HLA-DPA1, CD74, CD80) in both VAT and SAT." (PMID 36153324, 2022). "Then, at an early stage of adipose tissue inflammation, during the development of obesity, adipocyte MIF secretion directly facilitates M1 macrophage polarization via CD74, which is reported to be part of the MIF receptor complex." (PMID 31247902, 2019). "Interestingly, the targeted inhibition of CD74 attenuates adipose COX-2-MIF-mediated M1 macrophage polarization and abrogates obesity-related adipose tissue inflammation and insulin resistance." (PMID 36142162, 2022).
prostate carcinoma (11 papers, 2005 to 2025). A carcinoma that arises from epithelial cells of the prostate gland. "On the other hand, overexpression of the receptor CD74 was closely associated with growth and migration of prostate cancer cells." (PMID 38874510, 2024). "In the immune cell cluster of prostate cancer, formononetin targeted CD74, TNF, HBB, THBS1, INSR, CXCR4, and HSP90AA1." (PMID 38874510, 2024). "We also recently observed in vitro that reducing CD74 mRNA (using RNA interference) upregulated MIF in prostate cancer cells." (PMID 19503733, 2009). "Other recent studies have shown that anti-CD74 antibody blocks MIF-CD74 binding on the cell surface of gastric epithelial cells, and anti-CD74 antibody attenuated proliferation of prostate cancer cells." (PMID 19413900, 2009). "The expression of CD74 in the human prostate or its association with prostate cancer has not been investigated, but if MIF affects prostate cancer cell growth, then it is predicted that MIF's receptor should be localized within prostate tissue." (PMID 16000172, 2005). "Weak CD74 immunostaining was detected in both benign and prostate cancer tissues." (PMID 16000172, 2005). "Thus, the physiological relevance of CD74 in prostate cancer remains to be determined." (PMID 16000172, 2005). "The result of network pharmacology delineated the roles of formononetin’s targets such CD74 and THBS1 in immune cells’ function of prostate cancer." (PMID 38874510, 2024). "Other recent studies have demonstrated that anti-CD74 antibody blocks MIF-CD74 binding in the cell surface of gastric epithelial cells, and anti-CD74 antibody attenuated proliferation of prostate cancer cells." (PMID 19413900, 2009). "CD74 was found to be overexpressed in prostate cancer cell DU145, as compared with normal prostate cells, and blocking interaction of MIF with CD74 selectively inactivated ERK1/2, leading to reduced prostate cancer cell proliferation and increased apoptosis." (PMID 38874510, 2024). "In prostate cancer, MIF was intense but CD74 staining was weak and patchy." (PMID 24939415, 2014). "However, human benign prostate hyperplasia epithelial cells (BPH-1) and LNCaP prostate cancer cells do not express CD74 on the cell surface." (PMID 29190904, 2017).
Stroke (11 papers, 2011 to 2026). Sudden impairment of blood flow to a part of the brain due to occlusion or rupture of an artery to the brain. "A previous report suggested that elevated MIF and CD74 expression is linked to stroke clinical severity and causes a larger infarct size by activating and recruiting T cells." (PMID 35805977, 2022). "In contrast, at 4 and 8 weeks after stroke, the expression of Cd44, Spp1, and Cd74 (encoding CD44, Spp1, and CD74, respectively) was increased." (PMID 31888302, 2019). "The expression of CD74 is upregulated after ischemic stroke and is associated with stroke severity." (PMID 29633156, 2018). "The App‐Cd74 axis provides critical insights into the altered immune interactions that occur in various pathological conditions, including stroke." (PMID 41474773, 2026). "At 8 weeks post-stroke, the top 10 genes were Cd44 (degree = 14), Fcgr2b (degree = 13), C1qb (degree = 13), Cd74 (degree = 12), C1qc (degree = 11), Cd14 (degree = 10), C4a (degree = 10), Spp1 (degree = 10), RT1-A2 (degree = 9), and Itgb2 (degree = 9)." (PMID 31888302, 2019). "Furthermore, expression of genes encoding proteins involved in stabilization of MHC Class II molecules, the MHC Class II invariant chain (Cd74), and loading of peptide for antigen presentation (HLA-DM) were also downregulated after experimental stroke." (PMID 29872438, 2018). "Moreover, CD74 changes in blood may be useful as a biomarker for stroke." (PMID 29633156, 2018). "We found that CD74+ cells, putative APCs, accumulate in the brains of C57BL/6 mice during the first week after stroke." (PMID 21714902, 2011). "At 4 weeks post-stroke, the top 10 gene products in the PPI network were Cd44 (degree = 17), C1qb (degree = 15), Fcgr2b (degree = 14), Spp1 (degree = 12), Cd74 (degree = 12), C4a (degree = 12), C1qa (degree = 12), C3 (degree = 10), Cd14 (degree = 10), and Itgb2 (degree = 10)." (PMID 31888302, 2019). "CD74 is not expressed in brain cells, and the absence of MIF did not affect the number of CD74+ cells within the injured brain hemisphere, suggesting that the MIF-CD74 signaling is not involved in brain function after stroke." (PMID 21714902, 2011).
multiple sclerosis (10 papers, 2022 to 2025). A progressive autoimmune disorder affecting the central nervous system resulting in demyelination. "A CD74 subset was also described in the pathology of multiple sclerosis, and CD74 has been proposed as a marker for reactive microglia due to its increased expression levels in disease." (PMID 39640563, 2024). "CD74_Neu was widely present in PBMCs of multiple sclerosis, autoimmune lymphoproliferative syndrome cirrhotic, crohn ileitis, and chronic periodontitis." (PMID 38319415, 2024). "CD74 expression was lowest on transitional and naive B cells, which corresponds to previous observations in multiple sclerosis (MS)." (PMID 35837411, 2022). "On the other hand, the OL_7 subcluster expressed markers of immune cells such as C3, CD74, and CD83, therefore sharing a common transcription profile with the ImOLG population described in multiple sclerosis." (PMID 40293058, 2025).